HLA-H (major histocompatibility complex, class I, H (pseudogene))
Description:
Involved in the presentation of foreign antigens to the immune system.
Gene: Transcribed unprocessed pseudogene on chromosome 6 (29,887,752 to 29,890,482, forward strand). Ensembl gene ENSG00000206341.
Subcellular location: Cell membrane
Pathways (Reactome):
Immune System: Interferon alpha/beta signaling; Interferon gamma signaling
Diseases named in the same sentence as HLA-H in open-access papers:
HLA-H is named in the same sentence as 16 diseases in open-access papers, as found by Europe PMC text mining. Sharing a sentence is not in itself a finding about the gene and the disease. The quoted sentences say what the papers report.
Haemochromatosis (2 papers, 2016 to 2021). "At the same time, HLA-H gene mutations cause many cases of hereditary hemochromatosis." (PMID 34966413, 2021).
sarcoma (2 papers, 2021 to 2022). A usually aggressive malignant neoplasm of the soft tissue or bone. "One bioinformatic analysis reported that the overexpression of the lncRNAs ADAM6, C5orf58, CXCR2P1, FCGR2C, HCP5, HLA-H, NAPSB, NCF1B, and NCF1C reduced the sensitivity of sarcoma to ICIs." (PMID 36326232, 2022). "The expression of nine ICLs, ADAM6, C5orf58, CXCR2P1, FCGR2C, HCP5, HLA-H, NAPSB, NCF1B and NCF1C, was further investigated in different cancer types, including sarcoma." (PMID 34178688, 2021). "For C5orf58, HLA-H and NCF1C, a negative correlation of the expression of ICLs and DNA methylation was observed in sarcoma." (PMID 34178688, 2021).
cervical adenocarcinoma (1 paper, 2021). An adenocarcinoma arising from the cervical epithelium. "Third, Crest software was applied to detect a total of 743 SVs in 20 samples of cervical adenocarcinoma, revealing 34 fusion genes (e.g., HLA-H-HLA-A, APOL4-APOL1, and LINC00893-LINC00894), all with a positive rate among all samples of 15%." (PMID 33398034, 2021).
endometriosis (1 paper, 2014). The growth of functional endometrial tissue in anatomic sites outside the uterine body. "By contrast, in baboons treated overnight with a mixture of dKLAK-z13 and HLAH-z13, significant apoptosis was detected in endometriosis lesions." (PMID 25047118, 2014). "Histology of hematoxylin and eosin-stained tissue sections revealed evidence of endometriosis in all three animals treated with a mixture of dKLAK-z13 and HLAH-z13 peptides." (PMID 25047118, 2014). "We tested the effect of a mixture of dKLAK-z13 and HLAH-z13 peptides on baboon endometriosis models in vivo, as baboon endometriosis tissues were stained by anti-CNGB3 antibody in a similar manner as human endometriosis lesions are stained." (PMID 25047118, 2014).
lymph node metastasis (1 paper, 2020). "In addition, patients with lymph node metastasis had significantly higher expressions of PGM5P2, HERC2P4 and RRN3P2 but lower expressions of HLA-H and RPL13AP20 than those without lymph node metastasis." (PMID 33378744, 2020).
viral infections (1 paper, 2017). "It plays an essential role in iron homeostasis and C282Y mutation of HLA-H results in protein misfolding, which is associated with the iron overload and as we discussed impacts pathogenesis and treatment outcome of viral infections." (PMID 28769934, 2017). "Unfortunately, the role of HLA-H or HFE has been understudied in the context of viral infections." (PMID 28769934, 2017).
cancer (6 papers, 2021 to 2024). A tumor composed of atypical neoplastic, often pleomorphic cells that invade other tissues. "By exploring the specific functions of HLA-E, HLA-F, HLA-G, and HLA-H in various cancers, the authors aim to highlight their importance in the immune system’s interaction with tumors." (PMID 39766165, 2024). "Many HLA molecules, for example, HLA-E, HLA-F, HLA-G, HLA-H and HLA-DR were reported to be overexpressed on cancer cells." (PMID 36778644, 2023). "To achieve a comprehensive and objective evaluation of MHC-I expression in cancers, we developed a MHC-I signature score based on GSVA of eight MHC-I family genes, including HLA-A, HLA-B, HLA-C, HLA-D, HLA-E, HLA-F, HLA-H, and B2M." (PMID 39408874, 2024). "In recent years, non-classical HLAs—including HLA-E, HLA-F, HLA-G, and HLA-H—have emerged as critical players in the immune landscape of cancer due to their diverse and less conventional functions in immune modulation." (PMID 39766165, 2024). "There are classical forms, HLA-A, HLA-B, and HLA-C, and non-classical forms, HLA-G, HLA-E, HLA-F, and HLA-H, of this protein; both have been identified in cancer with diverse roles." (PMID 34359613, 2021).
tumor (4 papers, 2020 to 2025). "Of note, the HLA-H gene showed maximum association with clinical parameters including age (p = 0.048), sex (p = 0.023), tumor-stage (0.004) and T stage (p = 0.002)." (PMID 34834481, 2021). "Heatmap indicated that NCF1C, HLA-DRB6, HLA-DPB2, HLA-J, HLA-H, HLA-L and RPL13AP20 displayed high expressions in the low-risk group, and thus were categorized as tumor-suppressor pseudogenes in the current study." (PMID 33378744, 2020).
HLA-H also shares sentences with these, for which no sentence is quoted: breast carcinoma (3 papers); hemochromatosis (2); cervical carcinoma (1); chronic lung allograft dysfunction (1); chronic obstructive pulmonary disease (1); infection (1); melanoma (1); psoriasis (1).